RPLP2 (ribosomal protein lateral stalk subunit P2)
Description:
Plays an important role in the elongation step of protein synthesis.
Synonyms: D11S2243E; RPP2; P2; MGC71408; LP2
Tractability: PROTAC: ubiquitination databases record sites on it; its protein half-life has been measured.
Target class: Other cytosolic protein
Gene: Protein-coding gene on chromosome 11 (799,414 to 812,884, forward strand). Ensembl gene ENSG00000177600.
Subcellular location (Human Protein Atlas): Cytosol; Nuclear speckles; Mitotic spindle
Pathways (Reactome):
Metabolism of proteins: Eukaryotic Translation Termination; Formation of a pool of free 40S subunits; GTP hydrolysis and joining of the 60S ribosomal subunit; L13a-mediated translational silencing of Ceruloplasmin expression; PELO:HBS1L and ABCE1 dissociate a ribosome on a non-stop mRNA; Peptide chain elongation; Ribosome Quality Control (RQC) complex extracts and degrades nascent peptide; SRP-dependent cotranslational protein targeting to membrane; ZNF598 and the Ribosome-associated Quality Trigger (RQT) complex dissociate a ribosome stalled on a no-go mRNA
Metabolism of RNA: Major pathway of rRNA processing in the nucleolus and cytosol; Nonsense Mediated Decay (NMD) enhanced by the Exon Junction Complex (EJC); Nonsense Mediated Decay (NMD) independent of the Exon Junction Complex (EJC)
Cellular responses to stimuli: Response of EIF2AK4 (GCN2) to amino acid deficiency
Developmental Biology: Regulation of expression of SLITs and ROBOs
Disease: Viral mRNA Translation
Metabolism: Selenocysteine synthesis
Gene Ontology:
Molecular function: protein binding; structural constituent of ribosome
Biological process: cytoplasmic translation; negative regulation of myoblast fusion; spermatogenesis; striated muscle contraction; translation; cytoplasmic translational elongation; translational elongation
Cellular component: cytosolic large ribosomal subunit; extracellular exosome; focal adhesion; membrane; cytoplasm; cytosol; ribosome
Genetic constraint (gnomAD): Loss-of-function variants: 1 observed, 11.12 expected, observed/expected ratio (o/e) 0.0899, 90% interval 0.031 to 0.43. The synonymous counts are far from expectation, so gnomAD's model fits this gene poorly and the ratio says little. Missense variants: 177 observed, 144.07 expected, observed/expected ratio (o/e) 1.23, 90% interval 1.09 to 1.39. Synonymous variants: 82 observed, 58.03 expected, observed/expected ratio (o/e) 1.41, 90% interval 1.18 to 1.7.
Homologues: Orthologues: chimpanzee RPLP2 (100% identical), macaque RPLP2 (100% identical), mouse Rplp2 (99% identical), dog RPLP2 (98% identical), mouse Rplp2-ps1 (98% identical), rat Rplp2 (97% identical), guinea pig RPLP2 (97% identical), rat Rplp2l2 (97% identical), pig RPLP2 (96% identical), rat Rplp2l3 (94% identical), zebrafish rplp2l (76% identical), tropical clawed frog rplp2 (72% identical), and 2 more. Paralogues in human: RPLP0 (47% identical), RPLP1 (37% identical).
Diseases named in the same sentence as RPLP2 in open-access papers:
RPLP2 is named in the same sentence as 43 diseases in open-access papers, as found by Europe PMC text mining. Sharing a sentence is not in itself a finding about the gene and the disease. The quoted sentences say what the papers report.
COVID-19 (4 papers, 2021 to 2025). A disease caused by infection with severe acute respiratory syndrome coronavirus 2. "Two sets of three genes (CMB9-55F22.1, PIDD1, RPLP2), all of which are associated with the predominant lead COVID-19 hg-replicated SNP (rs3934992), constituted top 10% of statistically significant eGenes and sGenes, respectively." (PMID 34027315, 2021). "Among them, three (RPS28, RPLP2, and PDE12) had matching risk factor genes showing consistent patterns, i.e., transcriptional upregulations increased the COVID-19 mortality risk." (PMID 35547187, 2022). "In COVID-19, these included RPL13A, RPL6, RPL13, RPLP2, RPS11, UBA52, and the ribosomal pseudogene RPL13AP20." (PMID 41020849, 2025).
breast carcinoma (3 papers, 2022 to 2025). "A proteomic study utilizing bioinformatics analysis on breast cancer cell lines identified RPLP2 among other several genes correlated with chemotherapy-induced cancer cell death." (PMID 35622738, 2022). "RPLP2 and RPL37, both encoding for ribosomal proteins, were identified as tumor suppressor genes due to their silencing in breast cancer tissues." (PMID 35622738, 2022). "In breast cancer tissues, RPLP2 and RPL37 were found to be downregulated and their promoter region was hypermethylated." (PMID 35622738, 2022). "RPLP2 contributes to protein synthesis as an integral part of the ribosomal stalk and has been proven to play an essential role in regulating the occurrence and progression of the multiple cancers such as breast cancer, lung cancer, and liver cancer." (PMID 40564039, 2025). "In this study, for the first time, we report five oncogenes (TUBA1B, SLC2A1, PGK1, CCND1, and NCAPD2) and two tumor suppressors’ genes (RPLP2, RPL37) as novel therapeutic targets in breast cancer." (PMID 35622738, 2022). "But the TCGA analysis confirmed hypermethylation silencing of only the RPLP2 and RPL37 genes in human breast cancer tissues." (PMID 35622738, 2022). "For the first time in this study, we used a comprehensive in silico approach and identified five proto-oncogenes (TUBA1B, SLC2A1, PGK1, CCND1, and NCAPD2) and two tumor suppressor genes (RPLP2, RPL37) as novel therapeutic targets against breast cancer." (PMID 35622738, 2022).
hepatocellular carcinoma (3 papers, 2023 to 2024). A malignant tumor that arises from hepatocytes. "To elucidate the mechanism by which RPLP2 influences aerobic glycolysis in hepatoma cells and subsequently regulates proliferation, we employed lentivirus-mediated overexpression of HIF-1α (HIF-1α-OE) in Hep3B cells." (PMID 38052785, 2023). "For DSS, RPLP2 played a risk role in several subgroups, such as Stage III and IV, age ≤ 60, hepatocellular carcinoma and R0." (PMID 37980521, 2023). "Moreover, Guo and colleagues exhibited that Hepatocellular carcinoma progression is accelerated and prognosis is poor when RPLP2 is highly expressed because it inhibits ferroptosis." (PMID 39315094, 2024). "However, limited knowledge exists regarding the role of RPLP2 in hepatocellular carcinoma (HCC) progression." (PMID 38052785, 2023). "And the results indicated that the high level of RPLP2 predicted unfavorable OS in various subgroups including T1 and T2, T3 and T4, N0, M0, Stage III and IV, tumor free, age ≤ 60, hepatocellular carcinoma, R0, G3 and G4 and Child–Pugh grade A." (PMID 37980521, 2023).
liver cancer (3 papers, 2023 to 2025). An epithelial or non-epithelial malignant neoplasm that arises from the liver. "Mounting evidence proves that RPLP2 is upregulated and correlated with poor outcomes in many cancers, such as gynecological tumors, lung cancer, and liver cancer." (PMID 40564039, 2025). "Collectively, these findings indicate that overexpression of HIF-1α can restore the proliferative capacity of liver cancer cells suppressed by RPLP2 depletion." (PMID 38052785, 2023). "To investigate the role of RPLP2 in liver cancer pathogenesis, we examined its expression in liver cancer tissue using data from The Cancer Genome Atlas (TCGA) database." (PMID 38052785, 2023). "Considering the critical role of RPLP2 in promoting liver cancer, it’s necessary to search for drugs specifically targeting RPLP2 with high sensitivity." (PMID 37980521, 2023). "Importantly, RPLP2 regulates aerobic glycolysis and liver cancer cell proliferation via TLR4-mediated HIF-1α translocation into the nucleus." (PMID 38052785, 2023). "Moreover, the secretion levels of RPLP2 were higher in liver cancer cells, suggesting that it can have far-reaching effects after secretion into the extracellular space." (PMID 38052785, 2023). "Then, we detected the protein expression level of RPLP2 in normal liver cells WRL68 and several HCC cell lines, and the results showed that RPLP2 was elevated in liver cancer cells." (PMID 37980521, 2023). "In this study, we demonstrated that the autocrine function of RPLP2 in the extracellular domain promotes aerobic glycolysis in HCC cells by activating TLR4 and ultimately affects liver cancer cell proliferation." (PMID 38052785, 2023).
lung carcinoma (3 papers, 2023 to 2025). "Many studies have demonstrated that RPLP2 is highly expressed and associated with poor prognosis in various cancer types such as, breast, colon and lung cancers, and it may involve in carcinogens by affecting the translation of specific cellular mRNAs." (PMID 37980521, 2023). "Although the cell lines have different properties, in statin-treated lung cancer cells, RPLP2 expression was stable, whereas ACTB appeared to be an unstable internal reference gene." (PMID 37501994, 2023). "As a candidate oncogene, RPLP2 is overexpressed and closely associated with occurrence and progression of various cancers including but not limited to breast, ovarian, colon, lung cancer and AML, while there is no reports about the effect of RPLP2 on HCC." (PMID 37980521, 2023).
colon cancer (2 papers, 2018 to 2023). "Some groups have found that RPLP2 was related to gynecologic tumors 31, digestive system tumors such as colon cancer, and pancreatic cancer." (PMID 29522283, 2018). "RPLP2 is highly expressed in gynaecological tumours, colon cancer, and lung adenocarcinoma, and a lack of RPLP2 leads to the accumulation of reactive oxygen species (ROS) and activation of the MAPK1/ERK2 signalling pathway, which induces cancer cell cycle arrest and autophagy." (PMID 38052785, 2023).
dengue (2 papers, 2012 to 2024). "It would be then interesting to test if RPLP1 and RPLP2 knockdowns affect the luciferase activity from the dengue replicon at late time points, as observed upon GRK2 knockdown." (PMID 23029581, 2012). "Furthermore, RPLP2 was shown to be required for many flaviviruses such as dengue, yellow fever and zika virus." (PMID 39232783, 2024).
depression (2 papers, 2011 to 2021). "The other YWHAZ abnormalities were the interactions with RNPS1 and LGALS1 in schizophrenia; the interactions with MYCBP2, PRDX1 or TP1l in bipolar disorder; the interactions with RPLP2 and VIM in major depression; and the interactions with RPLP0 in both schizophrenia and major depression." (PMID 22373040, 2011).
hypercoagulability (2 papers, 2024 to 2025). "This study elucidated the action mechanism of XFC in RA inflammation and hypercoagulability through the lncDSCR9/RPLP2/PI3K/AKT axis." (PMID 39376558, 2024). "For elucidating lncDSCR9’s mechanism in modulating inflammation and hypercoagulability in RA, a pull-down assay coupled with mass spectrometry was employed, and RPLP2 was identified as the target of lncDSCR9." (PMID 39376558, 2024). "Similarly, Xinfeng capsule (XFC) has been shown to alleviate inflammation and hypercoagulability in RA by regulating the lncRNA down syndrome critical region 9 (DSCR9)/ribosomal protein lateral stalk subunit P2 (RPLP2)/phosphatidylinositol 3-kinase (PI3K)/protein kinase B, PKB (AKT) axis." (PMID 40453089, 2025).
lupus (2 papers, 2024 to 2025). "Prior research has documented significant upregulation of rpLP2 in systemic lupus erythematosus, severe hepatitis, nephritis, and certain malignancies, implying that dysregulated inflammatory responses are among its key pathogenic mechanisms." (PMID 40444038, 2025). "Next, we hypothesized that the anti-TCP1 antibody could be a better biomarker than the anti-RPLP0, RPLP1, and RPLP2 antibodies, which were already known lupus autoantibodies." (PMID 39201300, 2024).
ovarian carcinoma (2 papers, 2018 to 2023). A malignant neoplasm originating from the surface ovarian epithelium. "Many studies indicate that RPLP2 has been linked closely to the tumorigenesis, progression and malignant behavior of various cancers such as breast, lung and ovarian cancers." (PMID 37980521, 2023).
viral infection (2 papers, 2022 to 2024). "In a previous EPF genome-wide expression study (GWES), several genes involved in the early stages of viral infection were overexpressed in patients with the generalized form of EPF compared to healthy individuals, including IFITM3, APOBEC3A, APOBEC3G, OAS1, OASL, SERINC3, and RPLP2." (PMID 35632621, 2022).
autoimmune disease (1 paper, 2023). A disorder resulting from loss of function or tissue destruction of an organ or multiple organs, arising from humoral or cellular immune responses of the individual to their own tissue constituents. "The ribosomal stalk, consisting of acidic ribosomal proteins RPLP0, RPLP1, and RPLP2, played an essential role in promoting translation subsets of cellular mRNAs, and closely linked to several pathological conditions, including autoimmune diseases and human malignancies." (PMID 37980521, 2023).
cervical cancer (1 paper, 2018). A primary or metastatic malignant neoplasm involving the cervix. "Notably, PEG3, SPON1, BTD and RPLP2 passed the defined threshold of FDR <0.25, indicating the potential of these genes in showing their significances in cervical cancer." (PMID 30065881, 2018).
dry eye (1 paper, 2024). "A study comparing the tear fluid from pSS patients with that of non-SS dry eye subjects revealed upregulated protein metabolism involving MMP8, SERPINB5, RPLP2, CSTB, and CST3 in pSS patients compared to controls." (PMID 39408709, 2024).
duodenal cancers (1 paper, 2022). "Meanwhile, several upregulated genes in CRC malignant cells such as RPLP2, RPL36A, TFF3 have the increasing expression tendency in malignant cells from GC, duodenal cancers, jejunal cancers to CRC." (PMID 36104333, 2022).
endometrial cancer (1 paper, 2024). Primary or metastatic malignant neoplasm involving the endometrium (mucous membrane that lines the endometrial cavity). "Furthermore, compared with normal tissues, RPLP0, RPLP1and RPLP2 are significantly up-regulated in gynecologic tumors such as ovarian and endometrial cancers, suggesting that these proteins can be used as specific prognostic markers and related therapeutic targets for gynecological tumors." (PMID 39684863, 2024).
endometriosis (1 paper, 2016). The growth of functional endometrial tissue in anatomic sites outside the uterine body. "Among the selected genes, SNORD116, RPLP2, RPL38 and 40S ribosomal protein S28 (RPS28) were most elevated ones in endometriosis patients, which was consistent with our in vitro experimental findings using miR196a2-C vector." (PMID 27741504, 2016).
Heat Stroke (1 paper, 2025). A condition caused by the failure of body to dissipate heat in an excessively hot environment or during PHYSICAL EXERTION in a hot environment. "This investigation marks the inaugural demonstration of NM’s efficacy in heat stroke treatment, revealing its capacity to notably diminish the elevated plasma concentrations of IMPase 1, rpLP2, H4c16, and NGP in heat-stressed rats." (PMID 40444038, 2025). "Although no existing literature directly supports this, the pronounced inflammatory response observed in heat stroke may potentially trigger the marked elevation of rpLP2 levels." (PMID 40444038, 2025). "This study is the first to demonstrate substantial increases in IMPase 1, rpLP2, and NGP levels during heat stroke, correlating with the acute metabolic perturbations observed in this condition." (PMID 40444038, 2025).
influenza (1 paper, 2025). An acute viral infection of the respiratory tract, occurring in isolated cases, in epidemics, or in pandemics; it is caused by serologically different strains of viruses (influenzaviruses) designated A, B, and C, has a 3-day incubation period, and usually lasts for 3 to 10 days. "For influenza, discriminatory ribosomal genes included RPL7A, RPL13, RPL18, RPL23A, RPLP2, RPS2, and RPS4X." (PMID 41020849, 2025).
non-Hodgkin lymphoma (1 paper, 2025). Distinct from Hodgkin lymphoma both morphologically and biologically, non-Hodgkin lymphoma (NHL) is characterized by the absence of Reed-Sternberg cells, can occur at any age, and usually presents as a localized or generalized lymphadenopathy associated with fever and weight loss. "Additionally, Human Protein Atlas (HPA) data showed that RPLP2 mRNA expression was higher in DLBCL cell lines compared to lymph nodes, and the staining intensity of RPLP2 was greater in non-Hodgkin lymphoma (NHL) than in lymph node tissue." (PMID 40564039, 2025).
cancer (12 papers, 2018 to 2025). A tumor composed of atypical neoplastic, often pleomorphic cells that invade other tissues. "As a novel candidate oncogene, RPLP2 has been demonstrated to be upregulated and closely linked to the tumorigenesis of many cancers." (PMID 40564039, 2025). "We first conducted a pan-cancer analysis of RPLP2 mRNA expression based on TCGA and GTEx databases, and the results indicated that RPLP2 significantly increased in 21 different types of cancer, especially in DLBCL." (PMID 40564039, 2025). "Background/Objectives: Ribosomal Protein Lateral Stalk Subunit P2 (RPLP2), an important ribosomal protein, is mainly involved in modulating protein synthesis and plays an essential role in the carcinogenesis of many cancers." (PMID 40564039, 2025). "The results demonstrated that HCC tissues showed an obviously lower level of promoter methylation than normal liver tissues, and the expression level of RPLP2 was negatively correlated to the tumor grades and individual cancer stages separately." (PMID 37980521, 2023). "And GSEA results indicated that RPLP2 expression significantly alter the enrichment of several ferroptosis-related pathways in these five cancer types, especially in THYM." (PMID 37980521, 2023). "RPLP2, an integral part of ribosomal stalk, plays an important role in the tumorigenesis of various cancers." (PMID 37980521, 2023). "Additionally, the meaningful correlation between RPLP2 expression and different immune subtypes, suggesting us to explore the function of RPLP2 in cancer deeply by targeting specific immune subtypes." (PMID 37980521, 2023). "However, the specific role of RPLP2 in the development of DLBCL is unknown, and the possibility of targeting RPLP2 with specific inhibitors for cancer treatment remains to be explored." (PMID 40564039, 2025). "Silencing of RPLP2 may result in inhibition of proliferation of several cancer types of cells." (PMID 37980521, 2023). "Furthermore, the functional role of RPLP2 within tumour cells remains unknown, and whether it is involved in other cancer-promoting pathways requires further investigation." (PMID 38052785, 2023). "Moreover, our study demonstrated that RPLP2 interacts with TLR4 to promote cancer development." (PMID 38052785, 2023). "However, studies on the methylation level of RPLP2 in cancers are rare." (PMID 37980521, 2023). "Notably, we further explored whether RPLP2 upregulation was linked to ferroptosis in seven other cancers where RPLP2 was most significantly upregulated, and the results indicated that RPLP2 also showed significant correlation with GPX4 in five cancer types including GBM, LGG, PAAD, TGCT and THYM." (PMID 37980521, 2023). "The role of RBPs in promoting cancer has been confirmed, and DROSHA, EXOSC8, HNRNPC, MRPS31, RPLP2, and SNRPB have also been reported to be related to the occurrence and development of a variety of tumors." (PMID 33981333, 2021). "Considering the inhibitory effect of Destruxin b on a variety of cancers, including NHL, we further utilized the molecular protein interaction prediction model to predict the possibility of binding Destruxin b to RPLP2." (PMID 40564039, 2025). "Overlap of essential E‐boxes for four cancer cell lines revealed only three (1%) common E‐boxes: chr1_BS1363_CACAATG with neighbor genes MECR and PTPRU, chr11_BS79_CGCGTG localized near RPLP2 and PIDD1, and chr18_BS691_CATGTG adjacent to RBFA and TXNL4A." (PMID 37519063, 2023). "Therefore, the RPLP2/TLR4/PI3K/AKT axis provides a signalling pathway for regulating HIF-1α and subsequently promoting aerobic glycolysis and cancer cell growth." (PMID 38052785, 2023).